BRCA1 (BRCA1 DNA repair associated)
Diseases named in the same sentence as BRCA1 in open-access papers (continued):
Sharing a sentence is not in itself a finding about the gene and the disease.
breast cancer (continued). "Furthermore, the results of the present meta-analysis suggested that the BACH1 919Ser polymorphism may be correlated with a decreased risk of breast cancer in females with a family history of breast cancer and without BRCA1/2 mutations." (PMID 24137204, 2013). "However, further analysis of a significant number of BRCA1 and BRCA2 missense variants of uncertain significance (VUS) continue to pose an important obstacle to the clinical management of a considerable portion of familial breast cancer probands and families who carry such VUS." (PMID 23704879, 2013). "It is known that there is an interaction between HIF-1α and BRCA1 carrier cancers, but little has been reported about angiogenesis in BRCA1-2 carrier and BRCAX breast cancers." (PMID 23326384, 2013). "In a rodent model of breast cancer, DHA induced a reduction in mammary tumours accompanied by a 60% upregulation of BRCA1 tumour suppressor protein." (PMID 23762563, 2013). "Since then, several genetic analyses have shown some interplay between BRCA1 and THRA genes in breast cancers." (PMID 23805307, 2013). "Among the patients included in our study, five presented a family history of breast cancer in first-degree relatives, but only one case presented FANCA and BRCA1 alterations." (PMID 23483937, 2013). "BRCA1 (MIM 113705) and BRCA2 (MIM 600185) genes are responsible for approximately 20-40% of inherited breast cancer." (PMID 23683081, 2013). "In conclusion, the present meta-analysis indicated that the BACH1 919Ser polymorphism may decrease the risk of breast cancer among Caucasian populations, particularly in postmenopausal females with a family history of breast cancer and without BRCA1/2 mutations." (PMID 24137204, 2013). "A beneficial effect of pre-diagnosis bilateral oophorectomy on breast cancer-specific mortality has been reported in some, but not all, studies of women in the general population and among patient populations of women at high risk of developing breast cancer due to BRCA1/2 mutation status." (PMID 24152546, 2013). "In the present study, we have performed microarray gene expression profiling for molecular characterization and classification of BRCA1, BRCA2, and sporadic (unselected) breast cancers." (PMID 23704984, 2013). "The two BRCA1-defective breast cancer cells (HCC1937 and MDA-MB-436) shown to express low BRCA1 compared to the wild type cells." (PMID 23393598, 2013). "In the present study, we show similarities and concordance of BRCA1 protein localization between frozen and pressure cooker antigen-retrieved FFPE tissue in 22 randomly selected breast carcinomas." (PMID 23855721, 2013). "We compared BRCA1 protein localization in frozen and FFPE tissue, from 22 randomly selected patients with breast carcinomas." (PMID 23855721, 2013). "We identified 11 BRCA1 (11%) and 6 BRCA2 (6%) germline carriers among early-onset breast cancer patients." (PMID 22507745, 2012). "First, of the women in whom breast cancer developed at 35 years or younger, 28.0% of women with TNBC were BRCA1 or BRCA2 carriers compared with only 9.9% among those who developed non-TNBC (P = 0.045)." (PMID 23116406, 2012). "Besides the differences in number of cases with familial breast cancer history, the different sites of multiple-organ cancers might affect the many discrepancies in the prevalence of BRCA1/2 in multiple organ cancers cases between our study and the previous smaller study." (PMID 22382806, 2012). "However, it does not include information on BRCA1/2 mutation status or extended family history (meaning breast cancers in male relatives, number and breast cancer status/ovarian cancer status of second-degree relatives, and age of onset of all affected relatives)." (PMID 23127309, 2012).
breast cancer (continued). "The contribution of aberrant methylation alterations of BMP6, BRCA1 and P16 genes in lymph node metastasis might provide a further clue to establish useful biomarkers for screening metastasis, which might improve prognosis and therapeutic management of the breast cancer patients." (PMID 22695536, 2012). "MSH3 also directly and indirectly interacts with breast cancer susceptibility gene product (BRCA1) and BRCA1-associated RING domain protein 1 (BARD1) which may partially provide an explanation for the background of gynecological and CRC in both Lynch syndrome and BRCA1 individuals." (PMID 23209772, 2012). "Both these genes work in a similar way as BRCA1 and BRCA2, and this highlights the importance of these functions in preventing breast cancer." (PMID 23028338, 2012). "Induction of primary and invasive rat mammary tumors using the carcinogen N-methyl-N-nitrosourea (NMU), followed by analysis of rat BRCA1-IRIS and ERα mRNA levels in these tumors." (PMID 22511931, 2012). "However, it is also possible that the mechanism underlying susceptibility to breast cancer in non-BRCA1/2 families may not be due to truncating mutations in susceptibility genes." (PMID 22703186, 2012). "Particularly, ESR1, BRCA1 and BRCA2 were less often methylated compared with female breast cancer and were strong independent predictors of gender in logistic regression analysis (P = 0.005, P = 0.010 and P < 0.001, respectively)." (PMID 22765268, 2012). "Numbers of genes including BRCA1, COX-2, or estrogen receptor have been shown to play critical roles in the development of breast cancer." (PMID 22778704, 2012). "In contrast to female breast cancer (FBC) there was greater representation of BRCA2 tumours (41.7% vs 8.3%, p=0.0008) and underrepresentation of BRCA1 tumours (5.0% vs 14.4%, p=0.0001)." (PMID 23146383, 2012). "Canonical pathways that were assigned only to day 3 of estrous in the HR group (HR3>HR7) included role of BRCA1 in DNA damage response, ATM signaling, role of CHK proteins in cell cycle checkpoint control, and hereditary breast cancer signaling." (PMID 22952593, 2012). "Compared with female breast cancers (logistic regression), promoter hypermethylation was less common in a variety of genes, particularly ESR1 (P = 0.005), BRCA1 (P = 0.010) and BRCA2 (P < 0.001)." (PMID 22765268, 2012). "In breast cancer, multiple TSG are hypermethylated and downregulated, including for examples BRCA1, RASSF1A, p16, FHIT, and CDH1." (PMID 22110708, 2011). "Genomic analysis of BRCA1 and BRCA2 for 288 women who developed breast cancer was completed after entry into the trial." (PMID 22312502, 2011). "Using hierarchical clustering in the plasma samples cohort, we found significant promoter hypermethylation of eight genes (APC, BIN1, BRCA1, CST6, GSTP1, P16, P21 and TIMP3) in patients' plasma of breast cancer patients compared with plasma of normal subjects." (PMID 21283676, 2011). "BRCA1 and BRCA2 tumours have also been found to differ in terms of other tumour characteristics compared to breast cancers in the general population." (PMID 22053997, 2011). "We measured changes in telomere length in 19 mother-daughter pairs from FBOC families (3 BRCA1, 1 BRCA2, and 15 BRCAX) who developed breast cancer and compared them to 16 normal mother-daughter pairs." (PMID 21829373, 2011). "These included β-catenin-mediated transcription-related CALCOCO1, breast cancer poor-prognosis marker SBEM, and SMARCC2, a member of SWI/SNF chromatin-remodeling complex interacting with BRCA1." (PMID 21542898, 2011).
breast cancer (continued). "The occurrence of age anticipation in mother-daughter pairs with breast cancer was analyzed in 623 FBOC families, classified as BRCA1 (40 families), BRCA2 (52 families), and BRCAX (531 families)." (PMID 21829373, 2011). "This sequestration of BRCA1 and RAD51 to the cytoplasm has been observed both in cultured cell lines and in 60% of sporadic breast cancer tumors, in which it is correlated with the level of AKT1 activation." (PMID 21321378, 2010). "Hence, increasing the number of BRCA1 carriers identified by correctly selecting patients with a high probability of having hereditary breast cancer through a 10-year survival analysis could improve the benefit derived from specific chemotherapy agents (i.e., alkylating or PARP-inhibitors)." (PMID 20219108, 2010). "This approach would be similar to those that had pivotal roles in localising BRCA1 through using breast–ovary cancer families, and cloning BRCA2 through studying breast cancer families with male breast cancer." (PMID 20877337, 2010). "Thus, our group of controls is more likely to represent sporadic breast cancers than those identified through a genetic testing program, many of whom may have inherited breast cancers, although not through a germline BRCA1 or 2 mutation." (PMID 20149218, 2010). "DNA sequence data for BRCA1 and BRCA2 was obtained from 571 participants from the Australian Breast Cancer Family Study." (PMID 20807450, 2010). "The 10-year overall survival rate was 77% for BRCA1 carriers, 77% for BRCA-negative patients, and 73% for sporadic breast cancer (log-rank p < .001)." (PMID 20219108, 2010). "As no non-Jewish sporadic case (even the adopted individuals) reached the 10% combined threshold even at the time of diagnosis, this supports the hypothesis that, in Western populations, the rates of BRCA1/2 mutations even in early-onset breast cancer cases without a FH are low." (PMID 20234365, 2010). "A consistent finding in the few studies on human EOC tumors is that BRCA1 mRNA and protein are frequently expressed at low levels within cell nuclei relative to the commonly used positive tissue control MCF7, a breast cancer cell line." (PMID 20182637, 2010). "We provide clinical evidence in 41 patients for the role of post-treatment BRCA1 mRNA levels as a marker of TTP and OS in in sporadic breast cancer patients treated with anthacyclines." (PMID 20209131, 2010). "Mothers and sisters of women with breast cancer diagnosed before the age of 35 years were at a substantially increased risk of breast cancer, by a factor that remained high even for those whose index cases had been tested and found not to carry mutations in BRCA1 and BRCA2." (PMID 20877337, 2010). "Initially, the functional interaction between BRCA1 and Sp1 was suggested to regulate the IGF-I-R, a receptor overexpressed in most breast cancers that serves as an antiapoptotic factor." (PMID 20614009, 2010). "In basal-like breast cancer, the overexpression of ID4, a negative regulator of BRCA1, appears to also play a significant role in the deregulation of BRCA1, but further studies are needed to confirm these findings." (PMID 20979652, 2010). "BRCA1 and BRCA2 genes had been identified by linkage analysis and positional cloning on large breast cancer families in the early 1990's." (PMID 19656415, 2009). "Because of the embryonic lethality of homozygous animals carrying two defective Brca1 alleles and the lack of mammary tumour development in heterozygous mice carrying one defective and one wild-type Brca1 allele, these models could not be used to study the role of BRCA1 in tumorigenesis." (PMID 19904273, 2009).
breast cancer (continued). "Next, to examine the effects of silencing WT-BRCA1, by siRNA for BRCA1, on TGF-β mediated effects, MCF-7 breast cancer cells were either treated with si-GFP or siBRCA1." (PMID 19768112, 2009). "The finding that BRCA1/2 deficient cells are highly sensitive to PARP inhibition has opened a new avenue of research for treatment and prevention of tumors arising in the context of BRCA1/2 mutation or which might have somatic impairment of such pathways, such as basal-like breast cancer." (PMID 19825178, 2009). "We investigated some aspects of this intricate matter by sounding out the supposed relationship between BRCA1 and XIST expression/localisation and by assessing the nuclear XIST behaviour in breast cancer cells." (PMID 19440381, 2009). "We investigated a mouse model that closely mimics breast cancer arising in BRCA1-mutation carriers to better understand the molecular mechanism of tumor progression and tested whether targeting of the Polycomb-group protein EZH2 would be a putative therapy for BRCA1-deficient tumors." (PMID 19709408, 2009). "Therefore, our findings may not apply to a more general population of BRCA1/2 mutation carriers nor other women at high risk of breast cancer." (PMID 19602282, 2009). "Finally, the absence of any BRCA1 or BRCA2 mutation in majority of "high-risk" families with breast-ovarian cancer support the general hypothesis that additional breast cancer susceptibility genes remain to be identified." (PMID 19619314, 2009). "The study included 1,222 BRCA1 carriers (433 diagnosed with breast cancer) and 543 BRCA2 carriers (238 diagnosed with breast cancer)." (PMID 19843326, 2009). "In the presence of TGF-β1, H2O2 increased the BRCA1 and Smad3 interaction at the endogenous level in human keratinocyte HaCaT cells and wild type BRCA1-reconstituted HCC1937 breast cancer cells (HCCBRCA1)." (PMID 19768112, 2009). "Immunoperoxidase staining for HIF-1α, PHD1, PHD2, PHD3, VEGF and FIH was carried out in 125 (38 BRCA1, 33 BRCA2 and 54 BRCAX) breast carcinomas." (PMID 19724277, 2009). "We sequenced BRCA1/BRCA2 in 1,469 population-based female breast cancer patients diagnosed between the ages of 20 and 49 years." (PMID 18284688, 2008). "Using lysates from the MCF7 breast cancer cell line that harbors wild type BRCA1, we detected an interaction between endogenous SPT5 and BRCA1 by co-IP analysis." (PMID 18197258, 2008). "The present breast cancer risks represent the risks averaged over all possible polygenic and modifying effects and would therefore be applicable to a randomly chosen BRCA1 or BRCA2 mutation carrier (i.e., for a carrier without any knowledge of her family history)." (PMID 18349832, 2008). "Although our studies were limited in size and are not significant, the younger mean age of diagnosis of breast cancer in BRCA1 mutation carriers homozygous for the 72Pro allele is consistent with independent reports suggesting that this allele may modify penetrance of BRCA1 carriers." (PMID 18402691, 2008). "An additional recruitment category includes women aged 41 to 50 years who are found to be BRCA1 or BRCA2 gene carriers and were diagnosed with their first breast cancer during the study recruiting period." (PMID 17697367, 2007). "BRCA1 and BRCA2 can be identified in about half of the breast cancer patients with positive family history." (PMID 17233897, 2007). "Transcriptional elements involved in the regulation of the BRCA1 promoter were analysed by co-transfection experiments into the human MCF-7 and T-47D breast cancer cell lines." (PMID 17663789, 2007).
breast cancer (continued). "The uncertainties surrounding the most appropriate treatment of breast cancer in BRCA1 and BRCA2 gene carriers is of critical importance and must be resolved in order that clinicians can better tailor treatment in hereditary breast cancer." (PMID 17697367, 2007). "Our study assessed 112 high-risk breast cancer families for this variant, with our inclusion criteria (first inclusion criterion) being similar to those of Kato and colleagues aside from the fact that the BRCA1/2 mutation status was not reported in the Japanese study." (PMID 16762046, 2006). "For the breast cancer cells, increased BRCA2 protein levels were first observed after 4–8 h of I3C (60 μM); while increases in BRCA1 levels were detected earlier, but were relatively small in magnitude at early time points." (PMID 16434996, 2006). "We showed that two phytochemicals with potential cancer prevention activity, I3C and genistein, each upregulate expression of the BRCA1 and BRCA2 breast cancer genes." (PMID 16434996, 2006). "With regard to individual markers, the most striking difference between BRCA1 and BRCA2 hereditary breast carcinomas was in expression of cell cycle proteins." (PMID 16595007, 2006). "At our Institution, a programme of identification of healthy BRCA1-2 carriers is ongoing, starting with the determination of the BRCA status in patients with breast cancer and a significant family history." (PMID 15996267, 2005). "Besides family history, histopathological markers could also be useful in distinguishing patients and families likely to carry a BRCA1/2 germline mutation from mutation-negative families and breast cancer patients in general." (PMID 15642173, 2005). "However, it would be useful if, besides family history, histopathological markers could also be used to distinguish patients and families likely to carry a BRCA1/2 germline mutation from mutation-negative families and breast cancer patients in general." (PMID 15987451, 2005). "By comparison, the predictions under the BRCAPRO model are 3.7% and 0.6% for BRCA1 and BRCA2, respectively, for cases diagnosed under age 36 years and 1.8% and 0.4% for breast cancers diagnosed between ages 36 and 45 years." (PMID 15381934, 2004). "Invasive lobular BC is seen in 4% of BRCA1-related breast cancer and 4% of sporadic controls, whereas 11% of BRCA2-related breast cancer is of this subtype." (PMID 14735197, 2004). "It is estimated that BRCA1 and BRCA2 are responsible for 5 – 10% of breast cancer cases and 10% of ovarian cancer cases." (PMID 15138471, 2004). "Others have shown that steady-state BRCA1 mRNA levels are elevated in response to oestrogens in human breast cancer cells, and that BRCA2 expression is also regulated by oestrogens in human breast cancer cell lines." (PMID 12838319, 2003). "We have studied 50 randomly selected primary breast cancers by immunohistochemistry using MS110 and MS13 monoclonal antibodies to investigate the relation of BRCA1 expression to pathological, biological and survival parameters." (PMID 12698194, 2003). "In conclusion, the present study demonstrates that 30 μM resveratrol can increase expression of the BRCA1 and BRCA2 oncosuppressors, involved in the aggressiveness of human breast cancer cell lines." (PMID 12838319, 2003). "Estimates of the contribution of BRCA1 and BRCA2 to breast cancer incidence in outbred populations have been based on studies that are either small or have selected for cases diagnosed at an early age." (PMID 11044354, 2000). "We investigate allelic losses in microsatellites of the RAD51, RAD52, RAD54, BRCA1 and BRCA2 regions, and their correlations with nine pathologic parameters in 127 breast carcinomas." (PMID 10507777, 1999). "Regarding family history, breast cancer was the most common malignancy observed (71% in BRCA1 and 74% in BRCA2 families), followed by other cases of prostate cancer (42% in BRCA1 vs. 34% in BRCA2)." (PMID 41970070, 2026).